CRP (C-reactive protein)
Diseases named in the same sentence as CRP in open-access papers (continued):
Sharing a sentence is not in itself a finding about the gene and the disease.
intestinal obstruction (continued). "At 126/7 weeks, she had lost 6.0 kg in bodyweight with abdominal pain and no defecation: she was hospitalized for HG and suspected intestinal obstruction: laboratory data showed white blood cells, 9500/μL; hemoglobin, 13.8 mg/dL; hematocrit, 42.8%; and C-reactive protein (CRP), 18.0 mg/dL." (PMID 27597910, 2016).
Intraventricular hemorrhage (18 papers, 2013 to 2025). Bleeding into the ventricles of the brain. "After adjustment for WFNS grade, albumin, Fisher score, symptomatic cerebral vasospasm, age, intraventricular hemorrhage, and DCI, the CRP/albumin ratio was also an independent risk factor for poor outcome of aSAH." (PMID 31781024, 2019). "Neonatal complications (asphyxia, meconium aspiration, shock, and intraventricular hemorrhage) and maternal risk factors (prolonged labor, PROM) may also cause increase values of CRP." (PMID 38255436, 2024). "Poor outcome at 3 months was associated with a higher WFNS grade, higher serum glucose, higher CRP level, lower albumin level, higher Fisher score, higher CRP/albumin ratio, symptomatic cerebral vasospasm, intraventricular hemorrhage, delayed cerebral ischemia, and age using univariate analysis." (PMID 31781024, 2019). "CRP may rise physiologically after stressful delivery, intraventricular hemorrhage, fetal distress, perinatal asphyxia and meconium aspiration." (PMID 25280754, 2014). "Moreover, elevated CRP/albumin ratio was significantly associated with unfavorable 3-month outcome, even after adjustment for several factors, including WFNS grade, serum glucose, albumin, Fisher score, age, symptomatic cerebral vasospasm, intraventricular hemorrhage, and DCI." (PMID 31781024, 2019). "After adjustment for WFNS grade, serum glucose, albumin, Fisher score, age, symptomatic cerebral vasospasm, intraventricular hemorrhage, and DCI, the binary logistic regression identified CRP/albumin ratio to be independently related to poor outcomes in patients with aSAH." (PMID 31781024, 2019). "Raised CRP levels are not specific for bacterial infection, and might also appear in conditions as asphyxia, shock, intraventricular hemorrhage, surgery, and meconium aspiration." (PMID 35345614, 2022). "On the other hand, it cannot be forgotten that SAA, like CRP and PCT, rises up in response to non-infective stimuli, for example, stressful delivery and intraventricular hemorrhage, and that the role of GA in conditioning SAA levels is not definitively established." (PMID 37627653, 2023).
Liver abscess (18 papers, 2018 to 2026). A circumscribed area of pus or necrotic debris in the liver. "Numerous studies have shown that CRP levels are significantly elevated in infectious diseases, including liver abscess, and that persistent CRP elevation is often associated with poor prognosis." (PMID 41393139, 2025). "The six patients with liver abscess caused by C. difficile, whose cases are reported in the current literature, presented in the hospital with fever and localized abdominal pain, while five of them showed elevated C-reactive protein levels as well as impaired liver function tests." (PMID 40723972, 2025). "The heterogeneity of this cohort of liver abscesses, as with others in the literature, means that associations may have been missed and that those identified, such as higher CRP in ALAs and larger size in PLAs caused by streptococci, are too subtle to be of use to clinicians." (PMID 31159769, 2019). "Our study further confirmed that CRP is a sensitive biomarker for predicting IKPLAS in liver abscess patients, with elevated levels indicating worse clinical outcomes, while a decline in CRP suggests better prognosis." (PMID 41393139, 2025). "Our study demonstrated that the higher the CRP level, the higher the likelihood of liver abscesses infected by KP." (PMID 39392039, 2024). "The prominent clinical feature of this case was that the severe disease course started with severe infectious disease, which manifested as a liver abscess, and the patient had an intermittently high fever and increased CRP." (PMID 37038117, 2023). "We found a tendency toward higher C-reactive protein levels for patients with K. pneumoniae cryptogenic pyogenic liver abscesses." (PMID 29350134, 2018). "Laboratory results showed that inflammatory markers, such as white blood cells, erythrocyte sedimentation rate, and high-sensitivity C-reactive protein (hs-CRP) levels were higher in patients with large liver abscesses; conversely, procalcitonin (PCT) levels were lower." (PMID 33573593, 2021). "Despite liver abscess drainage, persistent fever, and no improvement in the WBC count or CRP level were observed." (PMID 36107543, 2022). "Despite liver abscess drainage, persistent fever and no improvement in the WBC count or CRP level was observed." (PMID 36107543, 2022). "In our cohort of patients with liver abscess we found no large differences in clinical parameters between pyogenic liver abscess (PLA) and amoebic liver abscess (ALA), other than weak evidence of higher baseline C-Reactive Protein (CRP) for ALA compared with PLA." (PMID 31159769, 2019).
multiple sclerosis (18 papers, 2015 to 2025). A progressive autoimmune disorder affecting the central nervous system resulting in demyelination. "Regardless of its origin (hepatic versus local), the presence of CRP in the CNS is associated with numerous diseases including Alzheimer's disease, amyotrophic lateral sclerosis, and multiple sclerosis (MS)." (PMID 26421184, 2015). "Seven markers were found to be significantly differently expressed in the serum of multiple sclerosis versus controls: osteopontin, Factor B, vitamin D binding protein, C5, iC3b, CRP and neurofilament light." (PMID 38368354, 2024). "DMF blocks a final common pathway of inflammasome signalling in vitro, and in keeping with this, DMF treatment normalises serum IL-1β in patients with multiple sclerosis and reduces serum CRP in an animal model of inflammation." (PMID 38296965, 2024). "A cluster of inflammation markers composed of blood leukocytes, CRP, and blood cell gene expression of IL17A and IL6 was positively associated with a cluster of multiple sclerosis-related species." (PMID 36604748, 2023). "In the case of multiple sclerosis, supplementation with vitamin A for 6 months increases the level of C-reactive protein (CRP), which is indicative of the level of inflammation." (PMID 25339542, 2015). "The present study aimed to evaluate the influence of omega‐3 fatty acids supplementation on the serum levels of brain‐derived neurotrophic factor (BDNF), high‐sensitivity C‐reactive protein (hs‐CRP), physical activity, and chronic fatigue in patients with multiple sclerosis (MS)." (PMID 40905016, 2025). "We recently demonstrated that human C-reactive protein (CRP), expressed hepatically in transgenic mice (CRPtg), improved the outcome of experimental autoimmune encephalomyelitis (EAE), a murine model of multiple sclerosis (MS)." (PMID 26421184, 2015). "For a more detailed analysis of the most frequently applied laboratory parameters of systemic inflammation (CRP and NLR), we divided the group of patients with multiple sclerosis into two subgroups, depending on clear signs of disease progression, determined by MRI." (PMID 38699700, 2024).
necrotizing enterocolitis (18 papers, 2011 to 2025). Necrotizing enterocolitis (NEC) is a devastating disease that affects mostly the intestine of premature infants. "PNGR is associated with a sustained elevation in C-reactive protein and increases the risk of PH, BPD and other diseases of prematurity including necrotizing enterocolitis (NEC), an inflammatory disease of the intestines." (PMID 32194566, 2020). "Indeed, among infants with false positive CRP results at T24, there were 8 postoperative infants and 14 who were treated for necrotizing enterocolitis, two conditions known to increase CRP values." (PMID 29382319, 2018). "The majority of serum CRP levels were obtained for post-operative monitoring (44/89 salivary samples), followed by necrotizing enterocolitis (NEC) or spontaneous intestinal perforation (SIP) (33/89 salivary samples), and infectious disease (12/89 salivary samples)." (PMID 25485262, 2014). "Also, the factors indirectly affecting bilirubin concentrations including inflammatory makers such as c reactive protein (CRP) or necrotizing enterocolitis (NEC) have rarely been taken into consideration for predicting bilirubin levels especially in preterm infants." (PMID 39806053, 2025). "We hypothesized that the serum CRP/ALB ratio has a prognostic value in predicting surgery and mortality in neonates with necrotizing enterocolitis (NEC)." (PMID 33779823, 2021). "The CRP, IL-6, IL-10, and IFN-γ in the serum of Necrotizing enterocolitis (NEC) intestinal stenosis patients were significantly higher than the reference values." (PMID 35958178, 2022).
Oral ulcer (18 papers, 2013 to 2026). Erosion of the mucous mebrane of the mouth with local excavation of the surface, resulting from the sloughing of inflammatory necrotic tissue. "The upregulation of complement C4 and CRP increased the risk of joint pain, butterfly rash and oral ulcer in RA patients (P<0.05)." (PMID 24223657, 2013). "PLHIV may be at high risk for COVID-19 pandemic induced-stress oral ulcers due to the elevated C-reactive protein, ferritin, and interleukin-6 that are also associated with oral ulcers." (PMID 37635219, 2023). "We found statistically significant positive associations with SLE disease activity index (SLEDAI) and damage index (SDI), physician and patient global assessment, C-reactive protein, leukocyturia, complement C4, IL-6 and oral ulcers." (PMID 38474267, 2024). "Despite exhibiting classic symptoms of herpangina including high fever, respiratory symptoms and oral ulcers, our patient’s elevated CRP level of 323.6 mg/L instigated further investigation into alternative bacterial infection sources." (PMID 39020267, 2024). "On the third day after the use of camrelizumab, the patient developed a marked skin rash accompanied by oral ulcers, hoarseness, and elevated CRP." (PMID 37124541, 2023). "In this regard, we observed a special phenomenon during the treatment of three patients: all three patients showed inflammatory reactions such as a surge in CRP, rash, and oral ulcer at different stages after combined treatment." (PMID 37124541, 2023). "At 22 months of age, he presented with recurrent episodes of unexplained fever, mouth ulcers and abdominal pain with intermittently elevated C-reactive protein (CRP)." (PMID 28830446, 2017). "Secondary outcomes were clinical feature scores (oral ulcers, eye lesions, genital ulcers, skin lesions, arthropathies, fever, and pathergy reactions) and laboratory index levels (erythrocyte sedimentation rate, C-reactive protein, and immunoglobulin A)." (PMID 34335839, 2021). "This suggests that when joint pain, butterfly rash and oral ulcer appear, patients with reductions in complement C3 and C4 levels and unchanged CRP levels may be diagnosed with SLE." (PMID 24223657, 2013). "The erythrocyte sedimentation rate (ESR), C-reactive protein (CRP) level, and skin lesions were also significantly improved using integrative medicine, but equivalent effects were seen for oral ulcers, genital ulcers, and eye inflammation." (PMID 33915947, 2021).
pneumothorax (18 papers, 2018 to 2026). Abnormal presence of air in the pleural cavity. "Our study shows that pneumothorax occurs relatively late (median 30 and mean 16 days from admission) in the course of disease, when CRP and fever were already down trending." (PMID 35930528, 2022). "In our study, it can be thought that the postoperative complications such as secondary pneumomediastinum and bilateral pneumothorax caused by intraoperative tracheal perforation in a patient in the TOETVA, and wound infection of another patient may affect the CRP values." (PMID 38033530, 2023).
tenosynovitis (18 papers, 2013 to 2025). Inflammation of the synovial lining of a tendon sheath. "Laboratory tests showed erythrocyte sedimentation rate (ESR) and C-reactive protein (CRP) levels above the upper limit and magnetic resonance imaging (MRI) of the hands and wrists revealed erosive arthritis and tenosynovitis of the extensor and flexor tendons." (PMID 39452543, 2024). "CRP (p < 0.0001), pain (p = 0.004), and PGA (p = 0.006) also demonstrated independent associations with MRI tenosynovitis." (PMID 32014018, 2020). "In a multivariable analysis that adjusted tenosynovitis for CRP and swollen joint count, the OR for tenosynovitis was 2.14 (95% CI 0.77–5.95)." (PMID 30764871, 2019). "Tenosynovitis was confirmed by MRI, and C reactive protein (CRP) was increased (2.7 mg/dl)." (PMID 37637139, 2023). "Also, significant correlation found between MSUS tenosynovitis and CRP (p = 0.04)." (PMID 23354165, 2013). "Diagnosis of tenosynovitis can be difficult because often no physical signs of acute or chronic infections exist, and erythrocyte sedimentation rate and C-reactive protein levels are typically normal." (PMID 33448712, 2021). "The predictive effect of tenosynovitis of the MCP joints remained present (OR 3.64, 95% 1.68–7.91), also after correction for other MRI inflammatory features and after correction for CRP and swollen joints (OR 3.61, 95% CI 1.50–8.65 and OR 2.64, 95% CI 1.14–6.16, respectively)." (PMID 30764871, 2019). "Furthermore, we found an association between the GS and PD tenosynovitis scores with TJC, SJC, DAS28-CRP, CRP, and SDAI and between the GS tenosynovitis score and CDAI." (PMID 28832684, 2017). "Laboratory data (CRP, ESR) and antibodies (RF IgM and ACPA positivity) as well as tenosynovitis/paratenonitis scores by GSUS and PDUS did not significantly predict erosions in ultrasonography." (PMID 23997769, 2013).
viral hepatitis (18 papers, 2015 to 2025). An acute or chronic inflammation of the liver parenchyma caused by viruses. "Elevated levels of baseline AFP, NLR, AAR, ALBI score, SII, and decreased CALLY index and N/CRP ratio were associated with vascular invasion and final tumor size in viral hepatitis." (PMID 40181742, 2025). "Among 30 172 NHANES adults from 7 cycles with available data on diet, CRP, leucocyte, and viral hepatitis, 512 individuals were anti-HCV positive and 126 individuals were HBV surface antigen positive." (PMID 36943385, 2023). "General Inflammatory biomarkers, such as C-reactive protein (CRP), and interleukin-6, have been associated with poor outcomes on viral hepatitis." (PMID 29033929, 2017). "Thus, the pooled mean CRP level could determine the level of liver damage in patients with viral Hepatitis." (PMID 40143267, 2025). "The other limitation of the current study is the lack of the laboratory results of ESR and CRP of the healthy control group, which prevents the detailed exploration of the mechanism for the cause of the neurocognitive deficit induced by viral hepatitis, especially HBV." (PMID 35739162, 2022). "Blood work was significant for electrolyte imbalance, elevated renal and liver functions, metabolic acidosis, elevated C-reactive protein, and negative autoimmune and viral hepatitis panel." (PMID 36475199, 2022). "HBV/HCV-positive patients significantly differed from healthy males with regard to both inflammatory markers and whole-blood leukocytes, while patients with no history of viral hepatitis only had higher hs-CRP serum levels than controls." (PMID 32430703, 2020). "Urine and blood were collected and revealed an infective bladder, elevated C-reactive protein (CRP), negative rheumatoid factor (RF), negative 2-mercaptoethanol test (2 ME), negative blood culture (B/C), negative HIV, negative viral hepatitis, and elevated erythrocyte sedimentation rate (ESR)." (PMID 35573053, 2022).
vitamin A deficiency (18 papers, 2012 to 2025). Deficiency of vitamin A due to malnutrition, malabsorption, or dietary lack. "Subclinical vitamin A deficiency, C-reactive protein, and nutritional status of pregnant women in eastern part of Ethiopia." (PMID 40248030, 2025). "Vitamin A deficiency was found to be significantly associated with infection as indicated by CRP and AGP levels." (PMID 36211493, 2022). "A simple decision rule {(−15.277 × [RBP, μmol/L] - 7.013 × [Transthyretin, μmol/L] + 0.367 × [C-reactive protein, mg/L] + 24.714) > 0.496} yielded prevalence estimates of vitamin A deficiency that is unbiased by diagnostic error." (PMID 25856672, 2015). "Vitamin A deficiency was associated with hemoglobin and CRP." (PMID 34495261, 2021). "A higher prevalence of vitamin A deficiency was found in children with infection, which is consistent with a study in Uganda of 661 children (6–59 months of age), demonstrating that infection status (measured by C reactive protein (CRP)) influenced the ELISA values for retinol-binding protein." (PMID 27551313, 2016). "The combination of transthyretin, RBP and C-reactive protein concentrations could eventually replace retinol concentration by HPLC in resource-poor settings as the preferred method to assess the population burden of vitamin A deficiency." (PMID 25856672, 2015). "The percentage of pregnant women classified differently between the two assays was 8 % for ID, 11 % for elevated CRP, 13 % for elevated AGP, 11 % for Fe-deficient erythropoiesis and 39 % for vitamin A deficiency." (PMID 37560803, 2024). "Children with elevated levels of CRP were approximately four times more likely to be diagnosed with low levels of RBP and vitamin A deficiency." (PMID 35245314, 2022). "Logistic regression resulted in a model of vitamin A deficiency dependent on RBP, transthyretin and C-reactive protein and a linear predictor of (−15.277 × [RBPμmol/L] - 7.013 × [Transthyretinμmol/L] + 0.367 × [C-reactive proteinmg/L] + 24.714)." (PMID 25856672, 2015). "It is suggested, therefore, to adjust serum ROL measurements with the concomitant values of inflammatory markers, such as C-reactive protein, in order not to overestimate vitamin A deficiency." (PMID 22296672, 2012). "Moreover, a prior study found a negative association between vitamin A and CRP levels, indicating that vitamin A deficiency is linked to elevated inflammatory responses." (PMID 36803946, 2022). "The estimated prevalence of vitamin A deficiency, whether measured by retinol or by RBP in children, increased with increasing AGP and CRP deciles in children but was not consistent in women for vitamin A insufficiency." (PMID 32743650, 2019).
Brain atrophy (17 papers, 2011 to 2025). Partial or complete wasting (loss) of brain tissue that was once present. "Separate lines of research have demonstrated that GWI is associated with elevated CRP, metabolic conditions, and with brain atrophy, and that protection from GWI is conferred by presence of specific Class II HLA alleles." (PMID 40371004, 2020). "In addition, elevated CRP levels have been associated with brain atrophy even in healthy people, highlighting the contribution of inflammatory markers on brain morphology independent of conditions that are typically associated with neurodegeneration." (PMID 40371004, 2020). "Elevated C-reactive protein (CRP) levels and inflammatory markers in MDD patients correlate with reduced cortical volume, suggesting systemic inflammation accelerates brain atrophy in susceptible individuals." (PMID 40244068, 2025). "Inflammatory markers, such as high levels of CRP have been found in the obese, where increased brain atrophy, increased white matter hyperintensities, and decreased total gray matter brain volume have also been observed." (PMID 35686024, 2022). "By multivariate linear regression analysis we demonstrated that the 24S-OH-Chol/TC ratio was significantly correlated with hs.CRP independent of age, albumin levels, brain atrophy, Babcock test, and FAB score (ANOVA: p:0.04; r2: 0.104)." (PMID 21970714, 2011).